GHR (growth hormone receptor)
Diseases named in the same sentence as GHR in open-access papers (continued):
Sharing a sentence is not in itself a finding about the gene and the disease.
acromegaly (continued). "We first confirmed expression of GHR in UC cells and assessed their response to GH stimulation and its inhibition by Pegvisomant, an FDA-approved GHR antagonist, used for the treatment of acromegaly." (PMID 40806252, 2025). "Conversely, acromegaly patients with the exon 3 deleted GHR (d3-GHR) isoform have a higher prevalence of VFs, regardless of disease activity." (PMID 41205005, 2025). "To further evaluate whether targeting GH action could serve as a therapeutic strategy, we confirmed GHR expression in NSCLC cells and examined their response in vitro to GH stimulation and inhibition by pegvisomant, an FDA-approved GHRA for acromegaly." (PMID 41515995, 2025). "These mice have intact GHR in all the tissues of the body, except for the liver; as a result, they present high GH, but low IGF-1 levels in the serum, having a form of extrahepatic acromegaly." (PMID 35665221, 2022). "When liver functions and reserve are normal, pegvisomant-mediated blockade of GH/GHR signaling results in decreased serum concentrations of total and free IGF-I, a growth-promoting cytokine in acromegaly and a survival-promoting cytokine for cancer cells, in humans." (PMID 36276070, 2022). "Moreover, specific inhibition of GHR was performed in vitro using siRNA and pegvisomant (a small peptide that blocks GHR signaling and is currently approved by the FDA to treat acromegaly) and in vivo, also using pegvisomant." (PMID 36276070, 2022). "More importantly, it provides the basis to investigate the potential integration of anti-GH strategies, such as pegvisomant; a short peptide that inhibits the GH/GHR signaling and is the only drug approved by FDA to treat acromegaly, into systemic therapy approaches in HCC." (PMID 36473155, 2022). "These hypothesized molecular mechanisms may justify the lower frequency of i-VFs in d3-GHR acromegaly carriers, treated with Peg-V, rather than to fl-GHR carrying ones." (PMID 39280003, 2024). "Additionally, tamoxifen offers an additional, oral treatment option for patients with acromegaly who might not achieve biochemical targets or cannot tolerate conventional medical therapy (such as somatostatin analogs or growth hormone receptor antagonists), though additional studies are necessary." (PMID 33910628, 2021). "Individuals with acromegaly (excess GH and IGF-1) have an increased incidence of cancers, while individuals with Laron Syndrome (congenital GH insensitivity due to non-functional GHR) are remarkably almost completely resistant to all cancers." (PMID 41515995, 2025).
Obesity (46 papers, 2007 to 2026). Accumulation of substantial excess body fat. "The ablation of GHR mRNA, deletion, and mutations in the GHR exons are related to human obesity, such as the increase of abdominal fat and subcutaneous fat content." (PMID 33519913, 2020). "It has been showed that GHR knockout would result in dwarfism, reduced body weight and obesity, and many SNPs in GHR gene were associated with fat deposition in human and chickens." (PMID 31208008, 2019). "A single study has looked at the adipose depots in lean and obese women and evaluated the level of full length GHR and the 1–279 variant and found a positive correlation of the variant with obesity in subcutaneous fat." (PMID 28486400, 2017). "Due to the dominant negative effect of the GHR variant, a decreased responsiveness to GH is expected with increasing obesity." (PMID 28486400, 2017). "We have previously reported that mice with genetic loss of growth hormone receptors (GHR) specifically in the skeletal muscle (mGHRKO model) are protected from high-fat diet (HFD)-induced obesity and insulin resistance." (PMID 23024761, 2012). "Growth and meat quality traits were evident through CAST (calpastatin, regulating muscle tenderness), FTO (fat mass and obesity‐associated gene, impacting fat deposition), GHR (growth hormone receptor) and MTOR (mechanistic target of rapamycin, controlling muscle protein synthesis)." (PMID 40859468, 2025). "Family of STAT protein involved in the growth hormone receptor (GHR) signaling pathway regulating growth hormone or somatotropin, involved in estrogen receptor pathway, and functional disruption causes infertility, obesity, hyperphagia, and thermal dysregulation." (PMID 35401673, 2022). "The recessive mutation of GHR results in the disruption of the affinity between GH and GHR protein and further inactivation of the GH–GHR–IGFs growth axis, leading to short stature, weight loss, and obesity." (PMID 33519913, 2020). "Furthermore, growth hormone receptor (GHR) deficiency improves insulinsensitivity and obesity-mediated leptin resistance in humans, and abrogated GHR signaling in mice reduces NLRP3activation that correlates with pro-longevity effects." (PMID 32292596, 2020). "STAT5 cannot be activated in GHR-KO mice, causing the enhancement of lipogenesis and obesity." (PMID 33519913, 2020). "The detailed mechanism underlying how GHR gene mutation or knockout result in obesity and abdominal fat deposition still remain unclear, especially in chickens." (PMID 31208008, 2019). "Moreover, reduced GHR expression and increased expression of truncated GHR (ΔGHR) in the AT results in a GH-resistant state that also contributes to the complications associated with obesity." (PMID 24795698, 2014). "Thus, deletion of GHR signaling in liver recapitulates the metabolic syndrome associated with obesity, which is itself a state of diminished GH secretion and hence diminished GH action on liver." (PMID 25566190, 2014). "In addition, select polymorphisms observed in patients with SGA include those involved in genes associated with obesity, type 2 diabetes, hypertension, ischemic heart disease and deletion of exon 3 growth hormone receptor (d3-GHR) polymorphism." (PMID 22587301, 2012). "In addition, we included obese wild-type animals fed on a high-fat diet to distinguish effects caused by obesity from the effects caused by the GHR mutations." (PMID 18648510, 2008). "However, once GHR exceeds this threshold, other risk factors, such as obesity, bile composition, and genetic predispositions, may play a more dominant role in gallstone pathogenesis, diminishing the relative contribution of GHR." (PMID 39950129, 2025). "The GHR-KO pig was recently developed as a large animal model for GH insensitivity and closely resembles the human phenotype regarding endocrine alterations, postnatal growth retardation and obesity as well as hallmarks of GH insensitivity-associated metabolism." (PMID 38960990, 2024).
Obesity (continued). "GHR-KO pigs reflect the phenotype of increased insulin sensitivity despite obesity observed in human LS patients." (PMID 41125144, 2025). "Remarkably, the expression pattern appeared less different than expected from the obvious degree of obesity in GHR-KO pigs." (PMID 41125144, 2025). "Growth hormone is important for skeletal and muscle growth, and mice with GHR knocked-out exhibit dwarfism while also tending toward obesity." (PMID 40369436, 2025). "Independent from obesity, expression of GHR, IGF-1 and IGFBP-3 was related to AT dysfunction,and increased insulin levels." (PMID 36384443, 2022). "We found that gene expression of GHR, IGF-1 and IGFBP-3 was compromised in AT of children with overweight/obesity and was associated with parameters of adipocyte function such as adipocyte hypertrophy and increased fasting insulin levels." (PMID 36384443, 2022). "GPX3, GHR and SAA1 were removed from further study because they have been reported previously to be associated with obesity." (PMID 33318306, 2020). "This phenomenon is similar to the results of GHR gene knockout in mice, which showed signs of obesity." (PMID 31208008, 2019). "As GH plays a role as a metabolic regulator, regulation of GHR expression is also controlled by factors including nutritional status, GH, insulin, and obesity/adiposity." (PMID 28486400, 2017). "Accordingly, the same authors also observed reduced GHR expression in adipocytes from obese individuals, which possibly coincide with local low-grade obesity-related inflammation." (PMID 28486400, 2017). "In the hyperinsulinemic state (as commonly occurs with obesity), higher insulin levels in the portal circulation in response to hyperglycemia upregulate the growth hormone receptor (GHR) and augment GHR signaling, increasing hepatic IGF-1 production." (PMID 24280167, 2013). "Notably, despite the increased fat mass, GHR-/- mice show features of “healthy obesity”, including elevated circulating adiponectin levels, which are thought to contribute to their metabolically protective phenotype." (PMID 41524828, 2026). "The GHR-KO pig particularly resembles the phenotype of Ecuadorian LS patients, where a preserved glucose tolerance despite decreased insulin secretion capacity results from an increased insulin sensitivity despite obesity." (PMID 38960990, 2024). "However, it must be considered that children with overweight/obesity have an increased AT mass and a higher number of adipocytes expressing GHR and IGF-1." (PMID 36384443, 2022). "As children with overweight/obesity showed reduced gene expression of GHR, IGF-1 and IGFBP-3 in subcutaneous adipocytes and SVF cells, we next analysed if local expression of these factors in adipocytes and SVF cells was associated with parameters of AT function." (PMID 36384443, 2022). "Therefore, we used gene editing technology to successfully knock out the GHR gene in pigs and establish the GHR KO model of LS; these animals showed typical dwarfism symptoms and obesity." (PMID 34803486, 2021). "The levels of hepatic GHR were also elevated in high-fat diet-induced obesity." (PMID 34373742, 2021). "To evaluate the role of hepatic GHR in metabolic regulation, we first determined the mRNA expression of GHR in the liver of obese subjects, which were collected from a cohort of age-matched healthy male subjects (BMI: 20.96 ± 3.41 kg/m2) and patients with obesity (BMI: 41.84 ± 4.89 kg/m2)." (PMID 34373742, 2021). "GHR expression in adipose tissue has been reported to be decreased in subjects with obesity." (PMID 34373742, 2021). "This shows that the effects of GHR mutation are clearly different from the effects of obesity and that the obesity in the mutant mice is likely to be a consequence of the low taurine levels and the GHR mutations rather than the converse." (PMID 18648510, 2008).
Obesity (continued). "In this paper we have shown that truncations in the intracellular domain of the GHR that impair STAT5 signaling in particular cause dramatic metabolic changes, leading to obesity, and involving the metabolism of the whole body, as evidenced by their consistency between liver tissue and urine." (PMID 18648510, 2008). "In conclusion, this study provides evidence for a role of GH/GHR/5-HT/HTR2B signaling during puberty in the control of β cell proliferation and mass, and it sheds light on the molecular pathways linking puberty and obesity to the risk of developing T2D later in life." (PMID 36107617, 2022). "We observed that gene expression of GHR and IGF-1 in adipocytes and expression of IGFBP-3 in SVF cells was decreased in children with overweight/obesity compared to lean children." (PMID 36384443, 2022). "Using the system biology approach, we mined a set of genes influenced by obesity to uncover five genes (FABP4, CFD, GHR, TNFRSF11B, and LTF) as previously unrecognized contributors to the development of TC." (PMID 33240576, 2020). "Five out of the 358 obesity-specific genes, FABP4, CFD, GHR, TNFRSF11B, and LTF, presented significantly decreased expression in TC patients (LFC<−1.44; and p-value < 1e−7)." (PMID 33240576, 2020). "Taken together, our results indicate that the increased accumulation of adipose tissue in GHR-KO pigs does not lead to the common obesity-related pathophysiology." (PMID 41125144, 2025). "Interestingly, gene expression dynamics of GHR, IGF-1 and IGFBP-3 was diminished in children with overweight/obesity compared to lean children." (PMID 36384443, 2022). "Furthermore, we assessed if gene expression of GHR, IGF-1 and IGFBP-3 in AT cells is related to overweight/obesity and AT function." (PMID 36384443, 2022). "Subjects with obesity have been reported to obtain higher IGF-I responses per dose level of hGH, possibly due to the interaction between GH and insulin on the hepatic GHR." (PMID 35521713, 2022). "In animals, dwarf, long-lived mice lacking the growth hormone receptor (GHR-/-) have reduced levels of IGF-1, are insulin sensitive despite obesity, and have decreased risk for cancer and diabetes." (PMID 25902704, 2015). "Obesity-related desensitization towards insulin action in adipose tissue is commonly associated with a reduced expression of the INSR, which was not the case in GHR-KO subcutaneous adipose tissue." (PMID 41125144, 2025). "Although nodose ganglia GHR expression was upregulated during pregnancy regardless of diet, GHR‐mediated downregulation of GVA responses to stretch may be impaired in obesity due to lower circulating GH abundance." (PMID 40023799, 2025). "Furthermore, in adipocytes from patients with severe obesity, the expression of GHRHR and GHR is increased compared to patients without obesity." (PMID 39560873, 2024).
dwarfism (43 papers, 2008 to 2025). "Mutations in GHR result in dwarfism in humans and animals, and the deletion of GHR creates dwarfism models in miniature pigs." (PMID 40520431, 2025). "It has been reported that loss-of-function mutations in GHR was related to sex-linked dwarfism in chicken." (PMID 38689225, 2024). "Today around 100 variants have been identified in the GHR gene that can cause dwarfism in humans, including missense, deletion, nonsense, frameshift and splice site variants." (PMID 37474955, 2023). "The GHR protein encoded by chickens with dwarfism is abnormal because of the mutation of the GHR gene, which cannot combine with growth hormone, resulting in growth retardation." (PMID 38002975, 2023). "Dwarfism is mostly caused by mutations in the GHR gene which is characterized by normal or elevated GH levels in serum and low levels of IGF." (PMID 37474955, 2023). "Laron syndrome, or primary GH insensitivity (OMIM#262500), is an autosomal recessive disease caused by mutations in the GHR gene, leading to GH resistance and dwarfism." (PMID 35283485, 2022). "On the Z chromosome, for example, a mutation in the growth hormone receptor (GHR) gene results in sex-linked dwarfism." (PMID 36436378, 2022). "Previous studies have shown that idiopathic dwarfism is associated with extremely low expression of GHR." (PMID 33461495, 2021). "This pattern of GHR, characterized by low expression and deficiency, is similar to that observed in many dwarfism diseases." (PMID 33461495, 2021). "To date, 93 GHR mutations related to human dwarfism and 4 GHR mutations associated with chicken dwarfism have been described." (PMID 29748515, 2018). "We summarized different mutations of the GHR gene and their possible mechanism relevant to human or chicken’s dwarfism." (PMID 29748515, 2018). "One of the best-studied hereditary variations in growth deficiency is sex-linked dwarfism, which is a proportional dwarfism, caused by the mutation in the GHR." (PMID 29930570, 2018). "Individual dwarfism caused by GHR disorders are LS and ISS in humans, miniature pigs, cattle and sheep, and sex-linked dwarfism (SLD) in chickens." (PMID 29748515, 2018). "GHR has been reported to contain a deletion in its exon as causative mutation for sex-linked dwarfism." (PMID 30425731, 2018). "This study contributes to our understanding of GHR mutations, including fragment deletions, point, missense, nonsense, splice site, and frameshift mutations, which not only contribute to individual dwarfism but also influence body bone development." (PMID 29748515, 2018). "An obvious candidate gene to be tested for the QTL on GGAZ is the growth hormone receptor gene, which is known to carry mutations that cause sex-linked dwarfism in chickens." (PMID 28427323, 2017). "Mutations in the GHR gene coding regions result in GH insensitivity (dwarfism) due to a dysfunctional receptor protein." (PMID 28557176, 2017). "In chicken, INDELs of 9–15 bp in PMEL17 gene are causative mutations for plumage color (Dominant white, Dun and Smoky) and an INDEL mutation in the growth hormone receptor (GHR) gene causes sex-linked dwarfism." (PMID 25133774, 2014). "Similarly, GHR-deficient mice (Laron mouse) exhibit severe postnatal growth retardation, proportionate dwarfism, and decreased serum IGF-1 levels." (PMID 40598150, 2025). "Although these findings in GHR‐deficient mice were confounded by dwarfism and increased adiposity, more recent studies of mice lacking GHR specifically in β‐cells demonstrated a blunted first‐phase GSIS and reduced β‐cell hyperplasia when mice were challenged with a high‐fat diet." (PMID 36480511, 2023). "This may be related to the breed’s lipid metabolism, which has been linked to sex-linked dwarfism in chickens caused by mutations in the growth hormone receptor gene on the Z chromosome." (PMID 37835672, 2023). "LS is caused by mutations and deletions of the GHR gene, leading to GH resistance and dwarfism." (PMID 35626664, 2022).